CD3G (CD3 gamma subunit of T-cell receptor complex)
Diseases named in the same sentence as CD3G in open-access papers (continued):
Sharing a sentence is not in itself a finding about the gene and the disease.
renal fibrosis (2 papers, 2024 to 2025). A final common manifestation of a wide variety of chronic kidney diseases characterized by glomerulosclerosis and tubulointerstitial fibrosis. "Through logistic analysis, tenfold cross-validation with LASSO, and gene topological analysis in Cytoscape, we pinpointed four core genes significantly associated with renal fibrosis: CD3G, CORO1A, FCGR2A, and GZMH." (PMID 38378674, 2024). "While in this study, drawing from transcriptome and single-cell sequencing data of patients with kidney fibrosis in public databases, we identified four core genes significantly associated with renal fibrosis, namely CD3G, CORO1A, FCGR2A, and GZMH." (PMID 38378674, 2024). "In summary, we identified five key genes (SFN, ARHGAP9, VSIG4, ISG20, CD3G) that can distinguish patients with renal fibrosis from controls, making them potential biomarkers for disease diagnosis and treatment monitoring." (PMID 41218386, 2025). "Logistic analysis, LASSO-based tenfold cross-validation, and gene topological analysis within Cytoscape identified four core genes (CD3G, CORO1A, FCGR2A, and GZMH) associated with renal fibrosis." (PMID 38378674, 2024).
Stroke (2 papers, 2022 to 2025). Sudden impairment of blood flow to a part of the brain due to occlusion or rupture of an artery to the brain. "The upregulation of Cd3d, Cd3e, Cd3g, Blnk, Sdc1, and Jchain suggests that chronic inflammation persists in peri-infarct regions for at least 7 weeks after stroke." (PMID 34819339, 2022). "Additionally, environmental stressors (e.g., PFOS exposure) that dysregulate CD3G expression highlight potential gene–environment interactions in CHIP‐stroke pathogenesis." (PMID 40702735, 2025).
adult T-cell leukemia (1 paper, 2022). "This was the most notable gene cluster which included the genes CD3D, CD3E, and CD3G which are part of the KEGG pathway for Human T-cell Leukemia Virus type 1 (HTLV-I) infection (KEGG pathway hsa05166), and HTLV-I infections are a known risk factor for developing adult T-cell leukemia/lymphoma." (PMID 35927608, 2022).
autoimmune hemolytic anemia (1 paper, 2024). Autoimmune hemolytic anemia (AIHA) is an autoimmune disorder in which various types of auto-antibodies are directed against red blood cells causing their survival to be shortened and resulting in hemolytic anemia. "CD3γ deficiency was diagnosed in two siblings presenting with recurrent infections (recurrent pneumonia, multiple abscesses and candidiasis), lymphoproliferation and autoimmune hemolytic anemia." (PMID 39072316, 2024).
B-cell lymphomas (1 paper, 2022). "Interestingly, HNL harbors a high prevalence of malaria leveraged gene variants related to hematopoietic function (e.g., CD3G) that may explain the high incidence of blood disorders such as B-cell lymphomas in the present-day HNL." (PMID 36173765, 2022). "Among these genes, we found five genes, ATP5L, BCL9L, CD3G, CXCR5, and DDX6, that have been reported to be associated with the occurrence of B-cell lymphomas, a blood cancer caused by the disorder of immune functional B cells (also known as B lymphocytes) that attack invading pathogens." (PMID 36173765, 2022).
childhood asthma (1 paper, 2022). "Second, while preliminary analyses revealed potential correlations between two key hub genes (CD3D and CD3G) and childhood asthma, further in-depth study is required, and the corresponding results need to be verified by further biological experiments." (PMID 36118895, 2022). "Using the weighted gene co-expression network analysis (WGCNA), CD3D and CD3G were identified as key genes closely correlated with childhood asthma." (PMID 36118895, 2022). "Interestingly, by intersecting these 20 overlapped genes with all hub genes, CD3D and CD3G were selected as key hub genes highly correlated with childhood asthma." (PMID 36118895, 2022). "Moreover, using WGCNA, CD3D, and CD3G were identified as key hub genes closely correlated with childhood asthma." (PMID 36118895, 2022). "Moreover, we also found that CD3D and CD3G might be involved in differentiation regulation of Th cell subsets in the process of childhood asthma." (PMID 36118895, 2022). "Thus, together with our results, we speculate that CD3D and CD3G may be functionally important for differentiation regulation of Th cell subsets in the process of childhood asthma." (PMID 36118895, 2022). "Results showed that the mRNA expression levels of CD3D, CD3G, HLA-DMB, CD69, RGS1, and CIITA were significantly upregulated in childhood asthma patients compared with healthy controls, consistent with bioinformatics analysis." (PMID 36118895, 2022). "Results showed that the mRNA levels of CD3D, CD3G, HLA-DMB, CD69, RGS1, and CIITA were significantly upregulated in childhood asthma patients compared with the control individuals." (PMID 36118895, 2022). "Based on qRT-PCR validation, CD3D, CD3G, HLA-DMB, CD69, RGS1, and CIITA were shown to be upregulated in childhood asthma patients." (PMID 36118895, 2022).
colorectal tumors (1 paper, 2023). "Further bioinformatic analyses revealed that several immune cell markers, including CCR7, CD40LG, and CD3G, were among the most positively correlated genes with DNASE1L3 in human colorectal tumors, indicative of a possible association between DNASE1L3 expression and antitumor immune activity." (PMID 37581941, 2023).
diffuse large B-cell lymphoma (1 paper, 2024). "(J) The CD3G+ T cells infiltration varied from colon to testis originating diffuse large B-cell lymphoma (DLBCL) in male (Fisher’s exact test)." (PMID 38980810, 2024).
endometrial cancer (1 paper, 2025). Primary or metastatic malignant neoplasm involving the endometrium (mucous membrane that lines the endometrial cavity). "This study is the first to explore the prognostic significance and immune activation roles of BATF, CD3G, KIAA1755 and CCL5 in endometrial cancer." (PMID 40356925, 2025).
enteritis (1 paper, 2023). Inflammation of the small intestine. "Here, we sought to determine whether IL-21 is produced by CD3γ/δ cells and, if so, whether the IL-21 producing CD3γ/δ cells are involved in enteritis." (PMID 37759501, 2023).
epilepsy (1 paper, 2025). A brain disorder characterized by episodes of abnormally increased neuronal discharge resulting in transient episodes of sensory or motor neurological dysfunction, or psychic dysfunction. "Previous study reported that severe immunodeficient phenotype of epilepsy with deletion of CD3D and CD3G may cause defective T cell development and lead to the early onset of the disease." (PMID 40697415, 2025). "In our research, both CD3D and CD3G were downregulated in epilepsy samples." (PMID 40697415, 2025). "Hence, we hypothesized that suppression of CD3D and CD3G expression limited T cell immune function and that impaired autoimmune function exacerbated the progression of epilepsy." (PMID 40697415, 2025). "CD3D, CD3G, CTSW, and JCHAIN were consistently expressed in the GSE143272 and GSE32534 datasets and all showed a low expression in epilepsy samples." (PMID 40697415, 2025). "Among them, we observed that the levels of CD3D, CD3G, CTSW, and JCHAIN were all significantly downregulated in epilepsy samples in the GSE143272 and GSE32534 datasets." (PMID 40697415, 2025). "Integrated transcriptomic and single-cell sequencing analyses identified CD3D, CD3G, CTSW, and JCHAIN as the key epilepsy genes that were also closely related to T cell function." (PMID 40697415, 2025). "A total of nine hub genes were screened in this study, in particular, four hub genes (CD3D, CD3G, CTSW, and JCHAIN) could effectively distinguish epilepsy samples." (PMID 40697415, 2025). "Second, the specific mechanism of the roles of CD3D, CD3G, CTSW, and JCHAIN in the development of epilepsy has not been verified by cell or animal experiments." (PMID 40697415, 2025).
glomerulonephritis (1 paper, 2025). A renal disorder characterized by damage in the glomeruli. "Glomerulonephritis samples additionally showed expression of collagen (COL1A1) and immune cell markers for monocytes or macrophages (LYZ and CD163) and T cells (CD3D, CD3E and CD3G)." (PMID 41028563, 2025).
liver cancer (1 paper, 2021). An epithelial or non-epithelial malignant neoplasm that arises from the liver. "CD3G gene polymorphism may affect the occurrence of liver cancer." (PMID 33388092, 2021).
multiple myeloma (1 paper, 2024). "Following the optimization of various pairs of two subunits of TCR/CD3 complex, B-3G-C-3E TRuC-T cells, characterized by incorporating CD3γ and CD3ε, exhibited the strongest myeloma-specific cytotoxicity." (PMID 39776916, 2024).
non-small cell lung carcinoma (1 paper, 2021). A group of at least three distinct histological types of lung cancer, including non-small cell squamous cell carcinoma, adenocarcinoma, and large cell carcinoma. "An insertion/deletion polymorphism in the CD3γ promoter was linked with increased hepatocellular carcinoma incidence, and another (rs3181259T>C) in CD3δ was linked to recurrence in non-small cell lung cancer (NSCLC)." (PMID 34012443, 2021).
scrapie (1 paper, 2012). A fatal disease of the nervous system in sheep and goats, characterized by pruritus, debility, and locomotor incoordination. "In contrast, the downregulation of CD3G observed in our natural model suggests that these cells are decreased in preclinical scrapie." (PMID 22897917, 2012).
thrombosis (1 paper, 2021). "At present, most of the research on CD3G focuses on tumors, and there are few reports on vascular diseases and thrombosis." (PMID 33388092, 2021).
tumor (50 papers, 2009 to 2026). "This was seen in conjunction with upregulation of genes associated with tumor-infiltrating lymphocyte (TIL) cytotoxicity (CD3G, SAP, PRF1, GZMM and GZMK)." (PMID 34084172, 2021). "Concurrently, we observed increased expression of genes associated with tumor infiltrating lymphocyte (TIL) cytotoxicity (CD3G, SAP, PRF1, GZMM and GZMK)." (PMID 34084172, 2021). "Genes such as CD3D and CD3G encode T cell surface glycoproteins and are well-known players in anti-tumor immunity." (PMID 32605588, 2020). "First, various immune associated genes like CD3G have been predicted, indicating the distinctive expression pattern in tumor and normal tissues." (PMID 29152097, 2017). "Expanding on this, CARs incorporating signaling domains from CD3δ or CD3γ in the context of the 41BB co-stimulatory domain show enhanced anti-tumor efficacy, reduced tonic signaling, and lower cytokine secretion compared to BBζ CARs." (PMID 41601693, 2026). "Consistent with this, spatial transcriptomic analysis using Xenium showed differential localization of T cells (Cd3d, Cd3e, Cd3g, Cd8a, Cd8b1, and Cd4) within tumor sections of RPR2 and CRPR2 mice." (PMID 41353272, 2025). "Then we used Loupe Browser 7.0 to group spots with gene characteristics (log2 count > 0) of CD68 or CD4 with CTLA4 as THC, and spots with gene characteristics of CD3D or CD3E or CD3G as tumor immune cells." (PMID 39499374, 2024). "CD3G is involved in T-cell development and signal transduction and has been reported to be associated with TME and prognosis in tumor patients." (PMID 36978709, 2023). "Conversely, the CD3G protein, which forms the TCR/CD3 complex and is expressed on the surface of T cells, exhibits potent antitumor activity by recognizing tumor-associated antigens and initiating intracellular signaling." (PMID 37284314, 2023). "We also found that several genes, including TYROBP, CD1C, KIR2DL3, CD3G, and TARP, were significantly highly expressed in patients with a high tumor mutational burden." (PMID 35204406, 2022). "T cells (expressing Cd2, Cd3e, Cd3g, and Cd6) were the most abundant immune cell type in tumor tissues, followed by cytotoxic cells (expressing Gzma and Klrd1)." (PMID 32612611, 2020). "The expression of CD3D, CD3G, CXCL9, and IRF1 were significantly associated with tumor stage and distant metastasis." (PMID 32925784, 2020). "The increase in cytotoxic cells was reinforced by induction of gene expression of the related gene Cd3g in Ats1-KO tumours." (PMID 30166561, 2018). "These evaluations also showed that the presence of tumours in WT mice provoked a slight but significant decrease in Cd3g, Il6 and Il12a expression in this immune organ." (PMID 30166561, 2018). "Has-miR-422a, has-miR-593 and has-miR-494 which represented other miRNAs predicted for CD3G also showed a similar decrease in levels in tumor tissues." (PMID 24244363, 2013). "This indicates that CD3G+ T cells in DLBCL may enhance the tumor antigen recognition process and stimulate the infiltration of immune cells, leading to an increased abundance of immune cell infiltration in the TME." (PMID 38980810, 2024). "The presence of CD3G+ T cells in the TME may contribute to a favorable prognosis by facilitating the activation of immune responses against tumor cells." (PMID 38980810, 2024). "However, anti-PD-L1 treatment resulted in upregulation or downregulation of numerous genes in CD45+ tumor-infiltrating immune cells in TCh3 tumors, including Cd3d, Cd3e, Cd3g, Cd8a, Cd8b1, Nkg7, Ccl5, Ets1, Icos, Cxcr6, Pdcd1, Lag3, Prf1, and Gzmb (right)." (PMID 35366939, 2022). "Moreover, the dual targeting CD19/CD3ε + TAG‐72/CD3δ or CD19/CD3ε + TAG‐72/CD3γ FP T cells killed TAG‐72hi CD19lo tumor cells, while the CD19/CD3ε single targeting FP T cells could not eradicate CD19lo cells." (PMID 38023726, 2023).
tumor (continued). "In addition, the activation of the NOD1 receptor induced by IE-DAP could upregulate TF STAT1, acting as an active transcription factor to boost tumor metastasis in PCa and upregulate the target gene CD3G." (PMID 35164166, 2022). "The cell types and markers we explored were as follows: tumor epithelial cells (E-cadherin as a marker), cancer-associated fibroblasts (CAFs; Collagen1A1), endothelial cells (Von Willebrand Factor [VWF]), the immune compartment (CD45), T cells (CD3G), myeloid cells (CD33), and macrophages (CD14)." (PMID 31765370, 2019). "VAV family proteins, CD3g, ZAP70 and LCK were down-regulated at four weeks in comparison to one week, suggesting a downregulation of T-cell response in PAK4KO tumour over time." (PMID 38797819, 2024). "We developed a novel immunohistochemical panel to assess prognostic outcomes and treatment sensitivity by detecting the expression of VCAN, CD3G, C1QB, CD68, CD4, and CD8 in both the TME and tumor cells of 190 DLBCL patients." (PMID 38980810, 2024). "The CD8 CTL is a subpopulation of tumor infiltrating T lymphocytes (TIL), which were commonly marked by CD3 (CD3G was used in our study, because it was the most abundant in the microarray)." (PMID 38557819, 2024). "Taken together, our findings underscore the significant roles of VCAN, CD3G, and C1QB, which influence both the TME and the behavior of tumor cells." (PMID 38980810, 2024). "CD3g and ZAP70 levels were significantly higher in PAK4KO tumour at one week but dropped to similar levels as WT tumour by four weeks." (PMID 38797819, 2024). "In line with this, we observed that tumours isolated from mice treated with RANO alone for 21 d expressed higher levels of Cd45, Cd3g and Cd8; a similar trend was observed with Cd4, which did however not reach significance." (PMID 37563469, 2023). "Immunohistochemical staining of the tumor tissue of one 51-year-old female LUAD patient showed some degree of protein expression of both CCL17 and CD3G (CD4/CD8+ T cell marker molecule)." (PMID 35321241, 2022). "We confirmed the restriction of SOX2 expression to tumor cells, PTPRC/CD45 to immune cells, SPI1/PU.1, CD68, and CD163 to ‘macrophages’, CD3G to ‘T cells’, and OLIG1/2 and MBP to oligodendrocytes." (PMID 35973991, 2022). "Compared with normal control tissues, the expression level of CD3D and CD2 in tumor tissues were not significantly different, while the expression levels of CD3E, CD3G, CCL5, CXCR6 and LCK in tumor tissues were lower than those in normal tissues (P < 0.05)." (PMID 34218795, 2021). "T and tumor cells were identified by the expression of classic cell type markers, including PTPRC, CD3G, CD3E, TRBC1, and CD8B for T cells and MAGEA 4 for MEL-526 cells." (PMID 33754038, 2021). "In relation to the increase in T cells, our results confirmed the induction of genes as Cd3g, Cd4, Il6, Il10 and Il12a in spleens of Ats1-KO mice, independently of the absence or presence of B16F1 tumours." (PMID 30166561, 2018). "Incorporating the cytoplasmic tails of CD3ε, CD3γ, and CD3δ into CAR constructs has been shown to improve anti-tumor responses, while lowering cytokine secretion and early exhaustion compared to second-generation ζCARs, challenging the current gold-standard of ζ-based CAR T-cell therapy." (PMID 41601693, 2026). "VCAN, CD3G, and C1QB were three key genes that influenced the tumor purity of DLBCL, and could also exert certain impact on drug sensitivity and prognosis of DLBCL patients." (PMID 38980810, 2024). "To ensure that the influence of our TEX signature was associated with survival independently of overall immune and T cell infiltration, we also included gene expression of CD8A, CD3G, and PTPRC in addition to patient age, tumor grade, tumor size, and LN status." (PMID 35132960, 2022).